PKHD1 (PKHD1 ciliary IPT domain containing fibrocystin/polyductin)
Diseases named in the same sentence as PKHD1 in open-access papers (continued):
Sharing a sentence is not in itself a finding about the gene and the disease.
autosomal recessive polycystic kidney disease (continued). "ECPKD was also enriched for PKHD1, which encodes fibrocystin, interacts with PKD1 and is associated with autosomal recessive polycystic kidney disease (PKD) (log2FC=0.96, adjusted P=1.1×10−56), although PKD1 was not within the list of DEGs." (PMID 40114603, 2025). "Another example could be Autosomal Recessive Polycystic Kidney Disease (ARPKD), which is a type of kidney disease that is caused by mutations in the PKHD1 gene, located on chromosome 6p12." (PMID 38785547, 2024). "Autosomal recessive polycystic kidney disease (ARPKD) is caused by a mutation in the polycystic kidney and hepatic disease-1 (PKHD1) gene and is an important inherited cause of chronic kidney disease in children." (PMID 38854310, 2024). "PKHD1 is associated with Autosomal Recessive Polycystic Kidney Disease (ARPKD)." (PMID 39408938, 2024). "PKHD1 gene is an essential factor leading to autosomal recessive polycystic kidney disease (ARPKD) in children." (PMID 36618928, 2022). "Autosomal recessive polycystic kidney disease (ARPKD) is a rare and severe renal cystic disease caused by homozygous or compound heterozygous variants of polycystic kidney and hepatic disease 1 (PKHD1) or DAZ interacting zinc finger protein 1 like (DZIP1L)." (PMID 34977057, 2021). "HNF1B is known to regulate transcription of polycystic kidney and hepatic disease (PKHD1), uromodulin (UMOD) and polycystic kidney disease 2 (PKD2)." (PMID 29576871, 2018). "Mutations in the PKHD1 gene cause autosomal recessive polycystic kidney disease (ARPKD)." (PMID 17357787, 2007). "In addition to the PCK rat, several mouse models of Pkhd1 gene disruption have been produced to model human autosomal recessive polycystic kidney disease (ARPKD) and congenital hepatic fibrosis (CHF)." (PMID 36097289, 2023). "Furthermore, experiments performed in hURECs from a patient with autosomal recessive polycystic kidney disease (ARPKD) and the PKHD1 variants revealed abnormally elongated cilia and the presence of multiple blebs along the axoneme." (PMID 38161384, 2023). "Fibrocystin/Polyductin (FPC), encoded by PKHD1, is associated with autosomal recessive polycystic kidney disease (ARPKD), yet its precise role in cystogenesis remains unclear." (PMID 37845212, 2023). "Although patients with PKHD1-associated autosomal recessive polycystic kidney disease often have liver abnormalities, none of the present four patients showed any clinically relevant liver involvement." (PMID 35211789, 2022). "The results indicate that transplantation with renal cells containing wild type Pkhd1 improves renal structure and function in autosomal recessive polycystic kidney disease and may provide an intra-renal supply of normal Pkhd1 mRNA." (PMID 26136112, 2015). "Additional members of this network are Ptprn2 (protein tyrosine phosphatase, receptor type, N polypeptide 2) and Pkhd1 (polycystic kidney and hepatic disease 1), which act i.e. as signaling molecule involved in cell growth, differentiation, mitotic cycle, and oncogenic transformation." (PMID 19812696, 2009). "Mutations in PKD1 and PKHD1 were identified in separate patients, representing autosomal dominant and autosomal recessive polycystic kidney disease (ADPKD and ARPKD), respectively." (PMID 41288877, 2025). "Some SNP variants occurred at genes linked to other renal diseases including autosomal dominant polycystic kidney disease (ADPKD) (Pkd1) and autosomal recessive polycystic kidney disease (ARPKD) (Pkhd1) and cystic fibrosis (Slc9A3R2)." (PMID 30606755, 2019). "Using PCK female rats, an orthologous model of autosomal recessive polycystic kidney disease harboring mutant Pkhd1, we tested the hypothesis that intravenous renal cell transplantation with normal Sprague Dawley male kidney cells would improve the polycystic kidney disease phenotype." (PMID 26136112, 2015).
autosomal recessive polycystic kidney disease (continued). "Autosomal recessive polycystic kidney disease (ARPKD; OMIM number 263200) is a single gene, severe hereditary form of polycystic kidney and liver disease caused by mutations in the PKHD1 gene." (PMID 25114813, 2014). "While the pathogenicity of the detected VUS remains unclear, given the patient’s clinical course and imaging findings, PKHD1-related autosomal recessive polycystic kidney disease (PKHD1-ARPKD) was deemed a likely diagnosis." (PMID 41255767, 2025). "Autosomal recessive polycystic kidney disease (ARPKD), a ciliopathy and main cause of endstage renal disease (ESRD) in children, originates from mutagenesis of the polycystic kidney and hepatic disease 1 (PKHD1) gene and loss of function of the encoded protein fibrocystin/polyductin (FPC)." (PMID 32698519, 2020).
polycystic kidney (29 papers, 2009 to 2025). "In Family 10 (P18–P19) and Family 11 (P20), the affected individuals carry heterozygous variants in genes (PKD1 and PKHD1, respectively) commonly associated with dominant and recessive polycystic kidney disease phenotypes." (PMID 41288877, 2025). "AGT and ACE variants were associated with renal tubular dysgenesis, while PKD1 and PKHD1 mutations indicated both dominant and recessive polycystic kidney disease." (PMID 41288877, 2025). "In fetuses with isolated renal anomalies, the highest detection rate of pathogenic variants was among fetuses with isolated polycystic kidney disease (29% PKHD1, PKHD1, PKD1, ETFA)." (PMID 37535131, 2024). "In one patient, two heterozygous missense variants were found in polycystic kidney and hepatic disease 1 (PKHD1), confirming polycystic kidney disease type 4." (PMID 34573383, 2021). "Collectively, these findings provide new insights on the pathophysiology of the polycystic kidney due to PKHD1 deficiency." (PMID 34977057, 2021). "Meanwhile, PKHD1 deficiency mice (PKHD1−/−) which develop spontaneously polycystic kidney and polycystic liver disease were also adopted in the present study." (PMID 32364232, 2020). "Mutations in the polycystic kidney and hepatic disease gene 1 (PKHD1) are responsible for this condition." (PMID 26257778, 2015). "It is caused by variants in the polycystic kidney and hepatic disease 1 (autosomal recessive) gene (PKHD1)." (PMID 25295861, 2014). "SMN, GHR and PKHD1 gene deletions respectively associated to spinal muscular atrophy, responsiveness to growth hormone and polycystic kidney disease were also detected using GStream." (PMID 23844243, 2013). "The mode of inheritance of polycystic kidney disease caused by the PKHD1 gene is thought to be recessive, however, in some cases, it has also been found that heterozygous carriers of mutations in the PKHD1 gene may develop liver and kidney phenotypes." (PMID 39015774, 2024). "Protein-protein interaction networks showed that the PKHD1 gene is a key gene in protein interaction networks by analyzing genes that may cause polycystic kidney phenotype." (PMID 39015774, 2024). "In the Indigenous Americans component, the strongest signal occurs in chr 6p12.3-2; this region harbors numerous genes, including IL17A which is associated with chronic inflammatory diseases such as rheumatoid arthritis, and PKHD1 which is associated with polycystic kidney disease." (PMID 22194699, 2011). "Polycystic kidney disease (PKD) was diagnosed in P15, P18, and P20, each carrying variants in PKD1, PKHD1, or with syndromic features suggestive of cystic pathologies." (PMID 41288877, 2025). "The three pathogenic variants were identified in the genes ACTA2 (multisystem smooth muscle dysfunction syndrome), PKHD1 (autosomal recessive form of polycystic kidney disease), and PKD1 (autosomal dominant polycystic kidney disease type 1)." (PMID 32779812, 2020). "Cytotherapy with renal cells expressing wild type Pkhd1 and tubulogenic serum amyloid A1 had powerful and sustained beneficial effects on renal function and structure in the polycystic kidney disease model." (PMID 26136112, 2015). "Subsequent homozygosity mapping defined a critical interval of 952 kb harboring 10 annotated genes and loci including the polycystic kidney and hepatic disease 1 (autosomal recessive) gene (PKHD1)." (PMID 25295861, 2014). "According to the decreased renal function and renal anemia due to polycystic kidney disease in Patient 5, we examined the PKHD1 gene related to ARPKD but no mutation was found." (PMID 32382272, 2020). "For example, Patient 5 was clinically associated with typical polycystic kidney disease with renal insufficiency; however, no mutations were found in the PKHD1 gene." (PMID 32382272, 2020). "Heterozygous mutation of PKHD1 and PKD1 was detected in two adults with polycystic kidneys." (PMID 32382272, 2020).
polycystic kidney (continued). "Using URECs directly derived from an adult patient with atypical polycystic kidney and no liver involvement, we validated the pathogenicity of a synonymous variant in PKHD1 and confirmed a genetic diagnosis of ARPKD." (PMID 33059616, 2020). "As briefly mentioned before, this set of variants and genes are mostly not known to be in cancer, except for PKHD1, a gene involved in polycystic kidney disease and associated with a higher risk of renal cancer." (PMID 28569218, 2017). "Mutations in POLR1C were recently shown to cause Treacher Collins syndrome and PKHD1 mutations are associated with polycystic kidney and hepatic disease and were thus excluded as candidate genes for PD." (PMID 22563501, 2012). "Moreover, an increased prevalence of liver neoplasms has been reported in patients with polycystic kidney disease, which indicated that the PKHD1 gene may be related to the occurrence of liver cancer, especially ICC10." (PMID 39512694, 2024). "For a direct role in the transcription of PKD2 and PKHD1, HNF1β has been recognized as a modifier in PKD, although mutations in HNF1B do not cause typical polycystic kidney disease." (PMID 33809516, 2021). "However, the specific role of the polycystic kidney and hepatic disease 1 (PKHD1) gene in ICC has not yet been evaluated." (PMID 39512694, 2024).
cystic kidney disease (28 papers, 2016 to 2025). A congenital or acquired kidney disorder characterized by the presence of renal cysts. "In contrast, truncating human PKHD1 mutations typically cause severe renal cystic disease during fetal life." (PMID 37584738, 2023). "The major defect of PKHD1 is postulated to result in dedifferentiation of cells, excessive secretion of fluid, and proliferation of tubular epithelia causing renal cysts." (PMID 34977057, 2021). "In our case, the common symptom between ARPKD and TSC was the renal cyst, however, PKHD1 mutations can only partially explain the phenotype of the patient." (PMID 34573383, 2021). "The transcription of PKHD1 is controlled by TCF-2 transcription factor, of which mutations impair PKHD1 transcription and result in renal cysts." (PMID 32276433, 2020). "Our previous NGS study of inherited cystic kidney diseases had identified 4 PKHD1 missense pathogenic mutations in 18 patients with suspected ARPKD." (PMID 32799815, 2020). "Here we use URECs to carry out RNA studies to validate the pathogenicity of a synonymous variant in PKHD1 and confirm a genetic diagnosis in an adult patient with atypical cystic kidney disease." (PMID 33059616, 2020). "HNF1B directly regulates the transcription of Pkhd1, and inhibition of PKHD1 gene expression may affect the development of renal cysts in humans with HNF1B mutations." (PMID 39337310, 2024). "Furthermore, we employed URECs to study the functional effects on ciliary phenotype of PKHD1 variants, since the protein product of PKHD1 was shown to localise to cilia and basal bodies, as the vast majority of genes associated to cystic kidney disease." (PMID 33059616, 2020). "PKHD1 is extensively glycosylated, and it is tempting to speculate that abnormal glycosylation of PKHD1 causes the biliary duct abnormalities and renal cysts." (PMID 31741824, 2019). "Given the role of HNF1β as a master regulator of a number of cystic kidney disease genes including PKHD1 and PKD2, there is a credible genetic cause which might explain the resemblance between HNF1β and ARPKD/ADPKD patients." (PMID 29479522, 2017). "Moreover, mutations in HNF1β can inhibit PKHD1 gene expression and may contribute to the formation of renal cysts in humans with MODY5 (maturity-onset diabetes of the young type 5) and congenital cystic abnormalities of the kidney." (PMID 28398236, 2017). "We describe two unrelated individuals with early onset cystic kidney disease and unaffected parents, where a combination of next-generation sequencing of cystic genes including PKHD1, HNF1B and PKD1 allowed the identification of biallelic PKD1 variants." (PMID 37372410, 2023). "In patients with pathogenic PKHD1 sequence variants, even partial loss of FPC function can result in dramatic renal cystic disease, suggesting that human FPC functions to maintain tubular integrity." (PMID 38125876, 2023). "Mutations in the gene encoding hepatocyte nuclear factor-1-beta (HNF1B) cause cystic kidney disease, and HNF1B has been shown to regulate expression of several cystogenic genes, including Pkhd1 and Cys1." (PMID 36710876, 2022). "There is emerging evidence that rare, predicted damaging variants within cystic kidney disease genes such as PKD2, HNF1B and PKHD1 may have a phenotype modifying role." (PMID 39883360, 2025). "We speculate that the minimal renal cystic disease in mouse Pkhd1 models reflects a combination of mechanisms." (PMID 37584738, 2023). "Pkhd1 deficient mice develop fibrocystic liver disease, but typically express either no renal phenotype or mild renal cystic disease." (PMID 36710876, 2022). "Pkd1flox/+:Pkhd1-Cre mice with Pkd1 deletion in one allele developed normally with no renal cyst formation up to 1 year." (PMID 34315885, 2021).
cystic kidney disease (continued). "The mild atypical cystic kidneys disease presentation in this case is consistent with mutations in PKHD1, however it is interesting that no signs of congenital hepatic fibrosis or other liver involvement are apparent, with normal platelet count also being observed in this patient." (PMID 33059616, 2020). "Inhibiting PKHD1 gene expression may result in human renal cyst formation." (PMID 31056860, 2019). "A cystic kidney disease panel should include adequate coverage of PKD1, PKD2, PKHD1, Daz-interacting zinc-finger protein 1-like (DZIP1L), HNF1B and genes for other ciliopathies such as nephronophthisis (NPHP) and Bardet–Biedl syndrome (BBS)." (PMID 31118499, 2019). "Virtually, all mutant Pkhd1 mice exhibit a liver phenotype resembling human disease, but renal cystic disease is either absent or very mild and slowly progressive." (PMID 37584738, 2023). "The renal phenotype of Pkhd1‐mutant mice differs from the presentation of ARPKD in humans, varying from a complete absence of kidney disease to slowly progressing late‐onset renal cysts, thus Cpk mice are widely used to model ARPKD." (PMID 39823139, 2025).
cyst (24 papers, 2015 to 2025). A sac-like closed membranous structure that may be empty or contain fluid or amorphous material. "PKHD1 encodes a protein called fibrocystin that is involved in kidney organogenesis, and mutation of PKHD1 gene is responsible for cyst formation in kidney." (PMID 35741793, 2022). "Development of collecting duct cysts in humans with presumed PKHD1 variants and mice with cystin deficiency suggests a shared pathobiology and possibly similar molecular mechanisms underlying cyst formation." (PMID 34521872, 2021). "The syndrome is linked to PKHD1 gene mutations, leading to ciliary dysfunction and cyst formation." (PMID 40248525, 2025). "However, the two genetic models for cyst pathogenesis in PKHD1 heterozygous mutation carriers require more clinical information to prove it." (PMID 39015774, 2024). "Other genes, including those encoding ciliary proteins, may contribute to cyst formation through synergistic heterozygosity, which could explain why only a subset of PKHD1 mutation carriers develop these liver or kidney findings." (PMID 39015774, 2024). "The upregulation of STING in cyst-lining epithelial cells in the kidneys of Pkd1RC/RC and Pkd1fl/fl: Pkhd1-Cre mice was further confirmed by immunofluorescence staining." (PMID 39456148, 2024). "Cy: cyst; Ctrl: age matched control animals from pooled litters; Mut: Invsflox/flox;Pkhd1-Cre mutant; Veh: vehicle treated." (PMID 36920028, 2023). "Treatment with liposomal clodronate to deplete phagocytic cells delayed cyst growth and improved renal function in Pkd1fl/fl:Pkhd1-Cre mice compared to vehicle treated animals." (PMID 35847973, 2022). "In support of this, we found that treatment with cystic cell EVs/exosomes induced tubular dilation and small cyst formation in 3-month old Pkd1flox/+:Pkhd1-Cre mouse kidneys." (PMID 34315885, 2021). "We found that treatment with GW4869 significantly delayed cyst growth in Pkd1RC/RC and Pkd1flox/flox:Pkhd1-Cre mice." (PMID 34315885, 2021). "Treatment with dasatinib led to inhibition of DDR1 tyrosine phosphorylation, slowed cyst growth and preserved renal function in Pkhd1-Cre; Pkd1fl/fl mice when compared with vehicle control treated mice, n = 6 mice/group." (PMID 31260458, 2019). "We also report that SD renal exosomes carry and transfer wild type Pkhd1 exo-mRNA and can limit cyst formation in matrigel matrices." (PMID 26136112, 2015). "Homozygous deletion of ILK (integrin-linked kinase) gene, whose product is a scaffold protein associated with multiple cellular functions including cell proliferation, resulted in increased caspase-3-mediated apoptosis and reduced cyst size of Pkd1fl/fl;Pkhd1-Cre mice." (PMID 35847973, 2022). "Interestingly, we found that treatment with cystic cell EVs/exosomes induced glomerular hypertrophy and promoted glomerular capillary loops to develop cyst-like structures in kidneys of Pkd1RC/RC mice and Pkd1flox/+:Pkhd1-Cre mice." (PMID 34315885, 2021). "In contrast to the Pkhd1-Cre model, deletion of PKD1 after postnatal day (PN) 14 leads to much slower cyst growth and loss of kidney function and, as a result, models in which PKD1 is inducibly deleted after PN day 14 are thought to more closely reflect disease in humans." (PMID 31260458, 2019). "In addition, some researchers have also suggested another possible genetic model for cyst pathogenesis that the polycystic liver phenotype in PKHD1 heterozygous carriers could occur through somatic second hit mutations." (PMID 39015774, 2024). "In contrast, PKD/PKHD1 mutations activate downstream events, such as cyclic adenosine monophosphate (cAMP), that promote cyst formation and cell proliferation, making it unclear whether repairing PKD/PKHD1 mutations can alleviate abnormal activation of downstream events." (PMID 40625571, 2023).